CLDN1 (claudin 1)
Diseases named in the same sentence as CLDN1 in open-access papers (continued):
Sharing a sentence is not in itself a finding about the gene and the disease.
liver fibrosis (6 papers, 2015 to 2025). "In WD-associated liver fibrosis, decreased expression of ileal tight junction proteins, including ZO-1 and claudin-1, are linked to intestinal barrier dysfunction." (PMID 40552147, 2025). "UA supplementation increased the expression of claudin-1 and occludin in the ileum of rats with CCl4-induced hepatic fibrosis." (PMID 39272277, 2024). "We found that the expression of occludin and claudin-1 in the rat intestinal tract decreased significantly in CCl4-induced liver fibrosis rats, while DOP enhanced the expression of these proteins." (PMID 32226380, 2020). "After QJ, the intestinal tissue structure of mice returned to normal, the expression levels of Claudin-1, Occludin and ZO-1 increased, the TJ apparatus damaged by CCl4 was restored, and liver inflammation and liver fibrosis were inhibited by repairing the intestinal epithelial barrier." (PMID 39234554, 2024).
bladder cancer (5 papers, 2013 to 2023). "Although previous immunohistochemistry studies have shown aberrant expression of claudin-1, -3, -4, and -7 proteins in human tissues of UTUC and bladder cancers, the expression of claudin-5 and its regulatory role in TJ homeostasis during UTUC tumorigenesis still remains elusive." (PMID 28829370, 2017).
cervical adenocarcinoma (5 papers, 2016 to 2024). An adenocarcinoma arising from the cervical epithelium. "The expression of F11R/JAM-A and claudin-1, 4, 7 proteins is significantly upregulated in patients with cervical adenocarcinoma and adenocarcinoma in situ (AIS)." (PMID 34533648, 2022). "Furthermore, in cervical adenocarcinoma, estrogen signaling through the GPER promotes claudin-1 production, contributing to cytoskeleton remodeling and enhancing malignant capabilities in cervical adenocarcinoma cells." (PMID 39409923, 2024). "Similarly, the expression of CLDN1 is upregulated by Akt in A54919 and cervical adenocarcinoma cells." (PMID 31551535, 2019). "Nonetheless, our previous study showed that CLDN1 expression in Siha cells derived from squmous carcinoma of cervix was significantly higher than that in Hela cells derived from adenocarcinoma of cervix(data not shown)." (PMID 27974683, 2016).
diabetic nephropathy (5 papers, 2014 to 2025). "The transgenic overexpression of claudin-1 in podocytes induces proteinuria in wild-type animals and aggravates streptozotocin-induced diabetic nephropathy." (PMID 25319473, 2014). "Furthermore, the impairment of intestinal barrier function in diabetic nephropathy (DN) rodents was validated via staining for occluding junctional proteins claudin-1 and ZO-1." (PMID 40458807, 2025). "According to an additional study, tropisetron may reduce oxidative damage and modify the levels of SIRT1, FOXO3a, and claudin-1, which could lessen renal damage brought on by diabetic nephropathy." (PMID 38629089, 2024). "SIRTs and claudin-1 are involved in metabolic disorders resulting from diabetic nephropathy." (PMID 35956936, 2022). "The role played by claudin-1 in podocyte injury is best exemplified by diabetic nephropathy." (PMID 25319473, 2014). "Further studies are needed to uncover whether Sirt1/Claudin-1 is important in the early stages and whether Nampt/Sirt6/TIMP-1 is significant in the middle to late stages of human diabetic nephropathy, similar to that in murine models." (PMID 38587753, 2024).
endometrial cancer (5 papers, 2017 to 2024). Primary or metastatic malignant neoplasm involving the endometrium (mucous membrane that lines the endometrial cavity). "A change in claudin-1 and claudin- 4 expression is also associated with endometrial cancer." (PMID 32197343, 2020). "Knockdown of LSR significantly induces Sp1 transcription factor activity in the CLDN-1 promoter region and promotes cell invasion via CLDN-1-mediated MMPs in endometrial cancer cells." (PMID 36961882, 2023). "Little is known about the precise molecular mechanisms underlying the activation of MMPs accompanying the expression of CLDN-1 in endometrial cancer tissues." (PMID 31330820, 2019). "We have also reported that downregulation of LSR promotes cell invasion via claudin-1-mediated MMPs in endometrial cancer cells." (PMID 28071680, 2017). "Furthermore, downregulation of angulin-1/LSR promotes cell invasion via upregulation of CLDN-1-mediated MMPs in endometrial cancer cells." (PMID 36961882, 2023). "During endometrial cancer progression, a decreased expression of LSR and increased expression of CLDN-1 have been observed." (PMID 31330820, 2019). "Moreover, the expression of claudin-4 is upregulated, while claudin-1 is downregulated as compared to normal endometrial cells, indicating that these proteins might be involved in endometrial tumorigenesis and could be helpful during the diagnosis of endometrial cancer." (PMID 32197343, 2020). "Following knockdown of LSR in endometrial cancer Sawano cells, CLDN-1 expression increased, while there was no significant change in the expression levels of CLDN-3, -4, -7, and OCLN." (PMID 31330820, 2019). "Using immunohistochemical analysis of paraffinized sections of endometrial cancer tissues, we observed a positive expression of LSR and negative expression of CLDN-1 in the gland-like structure region." (PMID 31330820, 2019).
follicular thyroid carcinoma (5 papers, 2019 to 2024). "Since claudin-1 expression is induced by the protein kinase C (PKC), the up-and-downregulation of PKC activity was directly associated with claudin-1 expression in follicular thyroid cancer (FTC) cells." (PMID 39458944, 2024). "Several studies have shown that upregulation of Claudin-1 is associated with increased cancer cell invasiveness and leads to worse prognosis in follicular thyroid cancer." (PMID 35818041, 2022). "However, high levels of claudin-1 were associated with increased aggressiveness of follicular thyroid carcinoma, implying that its role may be tissue-specific." (PMID 39458944, 2024). "Claudin-1 was found to be expressed in the membrane and cytoplasm in normal thyroid tissue, although it was found to be slightly expressed in the nucleus in follicular adenoma and primary follicular thyroid carcinoma." (PMID 35432533, 2022).
Hyperkeratosis (5 papers, 2020 to 2023). Hyperkeratosis is a histopathological term defining a thickened stratum corneum and may be present in many different skin conditions, with many possible overlaps. "It is interesting to note that the skin of a CLDN1-deficient mouse also shows signs of hyperkeratosis and acanthosis with age, suggesting that similar to humans, abnormal regulation of this protein affects multiple cellular mechanisms in mice." (PMID 37958945, 2023). "CLDN1-deficient mice exhibit signs of hyperkeratosis and acanthosis with aging, suggesting that abnormal regulation of this protein affects multiple cellular mechanisms." (PMID 32733073, 2020). "In the elderly, reduced levels of cldn-1 expression cause hyperkeratosis and acanthosis." (PMID 36836073, 2023). "When TJ barrier defects occur due to reduced expression or a complete absence of CLDN1, compensatory hyperkeratosis and acanthosis attempt to compensate for the loss of TJ barrier functions." (PMID 37958945, 2023). "Contrary to the mouse SC which also shows hyperkeratosis in the absence of Cldn1, the horny layer in humans appears to be better fit for providing the barrier function." (PMID 35806491, 2022).
non-small cell lung carcinoma (5 papers, 2017 to 2025). A group of at least three distinct histological types of lung cancer, including non-small cell squamous cell carcinoma, adenocarcinoma, and large cell carcinoma. "Over-expression of hsa-miR-375 down-regulates CLDN1, while knockdown of hsa-miR-375 up-regulates CLDN1 in non-small cell lung cancer." (PMID 40426863, 2025). "In non-small-cell lung cancer, CLDN1 is involved in the development of chemotherapeutic resistance to anticancer drugs such as cisplatin, doxorubicin, SN-38, and gemcitabine." (PMID 39457456, 2024). "Furthermore, CLDN1 activates autophagy and promotes resistance to cisplatin in non-small-cell lung cancer cells by upregulating Unc-51-like kinase 1 (ULK1) phosphorylation." (PMID 39457456, 2024). "Claudin-1 expression in non-small cell lung carcinoma is a good prognostic factor." (PMID 31044387, 2020).
pancreatic adenocarcinoma (5 papers, 2016 to 2024). "Taken together, LCA inhibits EMT by reducing the expression of EMT-related genes and Claudin-1 to reduce the invasion capacity of pancreatic adenocarcinoma cells." (PMID 38782891, 2024). "Interestingly, UDCA reduced the expression of tight junction protein, Claudin-1 whose reduced expression correlates with better survival in pancreatic adenocarcinoma patients." (PMID 39723238, 2024).
sclerosing cholangitis (5 papers, 2016 to 2023). A chronic, autoimmune inflammatory liver disorder characterized by narrowing and scarring of the lumen of the bile ducts. "An exonic mutation in cldn-1 can cause a human syndrome, called neonatal ichthyosis-sclerosing cholangitis." (PMID 36836073, 2023).
chronic kidney disease (4 papers, 2015 to 2022). Impairment of the renal function secondary to chronic kidney damage persisting for three or more months. "The results indicated that the protein expressions of ZO-1, claudin-1, and occludin-1 were decreased significantly in chronic kidney disease rats with the induction of adenine." (PMID 36160423, 2022). "In this study, the protein expressions of occludin-1, claudin-1, and ZO-1 were decreased significantly in chronic kidney disease rats with the induction of adenine." (PMID 36160423, 2022). "In a colonic inflammation model induced by chronic kidney disease (CKD), the Nrf2 activator, dh404, restored the levels of epithelial tight junction proteins including ZO-1, occludin, and claudin-1." (PMID 31346356, 2019).
food allergy (4 papers, 2016 to 2022). Gastrointestinal disturbances, skin eruptions, or shock due to allergic reactions to allergens in food. "Low levels of esophageal zonulin-3, claudin-1, and claudin-7 have been detected in patients with EoE, a disease that is closely associated with food allergy." (PMID 35844593, 2022). "A food allergen challenge induced a rapid degradation of intestinal intercellular junction proteins, including claudin-1, in a mouse model of food allergy." (PMID 35844593, 2022). "Expression of CLDN1 was previously found to be decreased in the distal small intestine of patients with food allergy." (PMID 31810340, 2019). "We therefore investigated whether baicalein could regulate intestinal barrier function in our mouse model of food allergy by examining the TJ proteins claudin-1, occludin, ZO-1, and JAM-1 in the intestinal epithelium." (PMID 27561877, 2016). "Food allergy reduced the expression of ZO-1 and Claudin-1 in intestinal epithelial cells, but did not affect Occludin expression." (PMID 34684316, 2021).
glioblastoma (4 papers, 2019 to 2026). The most malignant astrocytic tumor (WHO grade IV). "We found that the expressions of Claudin 1 and Occludin were significantly decreased in glioblastoma cells after treatment of TGF-β." (PMID 33613746, 2021). "In human glioblastoma multiforme claudin-1 was found to be downregulated in tumor vessels." (PMID 34867185, 2021).
head and neck cancer (4 papers, 2013 to 2025). A primary or metastatic malignant neoplasm affecting the head and neck. "Currently, there is an ongoing clinical trial that evaluated the efficacy and safety of ALE.C04 in monotherapy (first-in-class anti-claudin-1 monoclonal antibody) and combination with pembrolizumab (anti-PD-L1) in head and neck cancer (NCT06054477)." (PMID 39458944, 2024). "Hence, targeting the claudin-1/AMPK/TGF-β may prove as a plausible therapeutic target for head and neck cancer patients overexpressing claudin-1 and TGF-β." (PMID 37686483, 2023). "Inhibition of CLDN1 via monoclonal antibody was noted to be safe in nonhuman primates, with an active phase II clinical trial evaluating CLDN1 inhibition in patients with head and neck cancer (Clinicaltrials.gov NCT06054477)." (PMID 40955668, 2025).
Hepatitis (4 papers, 2017 to 2024). Inflammation of the liver. "Cldn1 is a pharmacological target since it is (i) an essential co-receptor for hepatitis C virus (HCV) infections and (ii) a key element of the epidermal barrier limiting drug delivery." (PMID 31561440, 2019).
lung squamous cell carcinoma (4 papers, 2017 to 2025). "CLDN1 is known to be highly expressed in lung squamous cell carcinoma." (PMID 28126724, 2017). "Both CLDN1 and CLDN11 were highly expressed in human lung squamous cell carcinoma (SCC)." (PMID 31551535, 2019).
preeclampsia (4 papers, 2021 to 2025). Preeclampsia is a hypertensive disorder of pregnancy that is characterized by new-onset hypertension with proteinuria presenting after 20 weeks of gestation, and depending on mild or severe forms may initially present with severe headache, visual disturbances, and hyperreflexia. "Our study demonstrated the association of CLDN1 and preeclampsia, which can offer a new potential therapeutic target for future clinical applications." (PMID 33784242, 2021). "The results of the qRT-PCR, Western blotting and immunohistochemistry experiments demonstrated that CLDN1 was significantly downregulated in the chorionic villi in samples from patients with preeclampsia." (PMID 33784242, 2021). "In contrast, this study combined four GEO datasets to compare the transcriptome of placenta in preeclampsia and normal pregnancy using bioinformatics analysis to demonstrate potential differential expression of the CLDN1 gene." (PMID 33784242, 2021). "Both the mRNA and protein levels of CLDN1 were decreased in the placental villi tissue of preeclampsia patients." (PMID 33784242, 2021). "Bioinformatics analysis was applied to find novel genes involved in the pathogenesis of preeclampsia and identified CLDN1 as one of the most differentially expressed genes when comparing patients with preeclampsia and healthy controls." (PMID 33784242, 2021). "CLDN1 could regulate trophoblast apoptosis and proliferation in preeclampsia, a gestational hypertensive disease." (PMID 40565529, 2025). "Overall, these results indicate that a decrease in CLDN1 inhibits BIRC3 expression and increases cleaved PARP levels thus participating in the pathogenesis of preeclampsia." (PMID 33784242, 2021). "In conclusion, we demonstrated that downregulation of CLDN1 regulates trophoblast apoptosis via a decrease in the levels of BIRC3 and downstream PARP, which is a new phenomenon in the pathogenesis of preeclampsia." (PMID 33784242, 2021).
renal fibrosis (4 papers, 2020 to 2022). A final common manifestation of a wide variety of chronic kidney diseases characterized by glomerulosclerosis and tubulointerstitial fibrosis. "Therefore, the up regulation of SIRT1, SIRT3 and SIRT4 and downregulation of Claudin 1 by MR extract might prevent renal fibrosis by suppressing mitochondrial oxidative stress and the production of inflammatory cytokines." (PMID 35956936, 2022).
tongue SCC (4 papers, 2021 to 2025). "Claudin 1 expression in cytoplasm along with the membrane was encountered at the invasive front of tongue SCC." (PMID 36714681, 2023). "Although we do not know why CLDN12 possesses distinct subcellular localization it has been reported that the CLDN1 localization is altered from cell membranes to cytoplasm at the invasion front of tongue SCC tissues." (PMID 33917356, 2021). "In addition, CAPS in combination with cisplatin suppresses transforming growth factor-β1-induced epithelial–mesenchymal transition (EMT) through the activation of claudin 1 and inhibition of the PI3K/AKT/mTOR pathway in squamous cell carcinoma of the tongue." (PMID 39519591, 2024).
allergic disease (3 papers, 2018 to 2022). An immune response that occurs following re-exposure to an innocuous antigen, and that requires the presence of existing antibodies against that antigen. "The claudin-1 expression level was significantly downregulated in the esophagus of patients with EoE, an allergic disease associated with food antigens." (PMID 35844593, 2022). "The reduced expression level of claudin-1 may cause tight junction dysfunction, and it has been suggested to be a key mechanism for allergic diseases of the skin, airways, and GI tract." (PMID 35844593, 2022). "Particularly, we found that the expression level of claudin-1 in epithelial cells is commonly downregulated in allergic diseases of the skin, lungs, and GI tract." (PMID 35844593, 2022). "In the present study, we reviewed the involvement of epithelial barriers and tight junction proteins in allergic diseases, and hypothesized that claudin-1-mediated tight junction dysfunction could contribute to atopic march." (PMID 35844593, 2022). "However, the evidence only demonstrated separate correlations between claudin-1 expression level and allergic diseases of the skin, airways, and GI tract." (PMID 35844593, 2022). "The hypothesis, “claudin-1-mediated tight junction dysfunction contributes to atopic march”, is mainly supported by three lines of evidence: clinical observations, animal models of allergic diseases, and CLDN-1 knockdown studies." (PMID 35844593, 2022). "Besides, a direct pathogenetic role of claudin-1 knockdown in AD and AA was confirmed, suggesting that downregulation of claudin-1 expression level contributes to the pathogenesis of these allergic diseases." (PMID 35844593, 2022). "Therefore, our hypothesis that downregulation of claudin-1 expression level contributes to the atopic march is well supported with separate evidence concerning each of the involved allergic diseases." (PMID 35844593, 2022).
cholangiocarcinoma (3 papers, 2015 to 2020). A carcinoma that arises from the intrahepatic biliary tree (intrahepatic cholangiocarcinoma) or from the junction, or adjacent to the junction, of the right and left hepatic ducts (hilar cholangiocarcinoma). "Here, we demonstrate evidence to support the use of a panel of fluorescently labeled peptides specific for EGFR, claudin-1, and ErbB2 to distinguish BilIN, the precursor lesion, and cholangiocarcinoma from normal biliary epithelium." (PMID 36345439, 2020). "Here, we hypothesized that EGFR, claudin-1, and ErbB2 are over expressed on the cell surface in BilINs, the precursor lesion, and in cholangiocarcinoma, and can serve as targets for multiplexed imaging for future in vivo imaging to distinguish indeterminant biliary strictures." (PMID 36345439, 2020). "To investigate HCV entry factor expression in vivo we stained cholangiocarcinoma liver tissue from two donors with antibodies specific for CD81, SR-BI, claudin-1, occludin and epithelial marker CK19." (PMID 25701818, 2015).
cholestasis (3 papers, 2013 to 2024). Impairment of the bile flow caused by obstruction within the liver, or outside the liver in the bile duct system. "TJP2 mutations prevent CLDN1 from localizing to this membrane, reducing its integrity and allowing toxic bile acids to leak into hepatocytes and cause damage and cholestasis." (PMID 39697951, 2024). "The up-regulation of the tight junction-associated proteins occluding and claudin-1 is mainly attributable to the reflux of pancreatic juice into common bile duct and cholestasis in PBM." (PMID 26772979, 2016). "At the same time, our observation that claudin-1 was up-regulated in the epithelial cells of the common bile duct of PBM patients suggests that cholestasis alone may not explain all our findings." (PMID 26772979, 2016).